AKT2 (AKT serine/threonine kinase 2)
Diseases named in the same sentence as AKT2 in open-access papers (continued):
Sharing a sentence is not in itself a finding about the gene and the disease.
infection (continued). "In addition, LGTV-infected AKT1 KO and AKT2 KO cells had higher levels of either AKT2 or AKT1, respectively, than WT cells, further suggesting that depletion of one of these isoforms causes a decrease in pAKT during infection." (PMID 32977414, 2020). "In addition, our study showed that patients with leukocytopenia after infection exhibited abnormal hypermethylation of AKT2 and that inhibiting the PI3K/AKT pathway could strengthen mitochondrial autophagy in macrophages, which in turn alleviated the pulmonary inflammatory response." (PMID 37077346, 2023). "Both Akt1 and Akt2 were demonstrated to phosphorylate PDK1, and PDK4 expression was markedly inhibited by infection with shRNA directed against Akt1." (PMID 31398213, 2019). "Transient expression of OIP5 by infection with Ad-OIP5 also increased the phosphorylation of AKT1 and AKT2 in HLK3 and SH-J1 cells." (PMID 28184024, 2017). "To genetically confirm the role of various AKT isoforms in macrophage infection, we knocked down the expression of AKT1, AKT2, and AKT3 in J774 macrophages." (PMID 24586159, 2014). "The AKT2 inhibitor group exhibited significantly increased levels of LC3B and Beclin1 compared with the control group (P < 0.05), and the Beclin1 level was significantly higher than that in the infection model group (P < 0.05)." (PMID 37077346, 2023). "Although the infection does not change the expression levels of Akt1 and Akt2 mRNA and proteins, the phosphorylated forms of these proteins are upregulated in the heart tissue of infected mice compared to the uninfected group." (PMID 29666415, 2018). "In contrast, p38γ and particularly Akt (i.e., Akt1, Akt2 and Aktpan, but not Akt3) appeared strongly phosphorylated after infection with parental virus but only weakly after infection with ORF4−Tet+ (data not shown)." (PMID 20657771, 2010). "Infection with AKT2 or AKT3 did not rescue either WT or GRP94 KD cells from death (not shown)." (PMID 38811543, 2024). "Interestingly, the presence of either Akt2 or Akt3 does not affect sNAG stimulated wound repair and tensile strength as discussed here, or the clearance of infection and wound closure as previously reported." (PMID 25955155, 2015). "Moreover, kinases found to be upregulated by the infection of HIBCPP cells with both N. meningitidis strains in this analysis (downregulated in control cells) include MAPKAPK2, RPS6KB1, RET as well as AKT1 and AKT2, whereas PRKACA activity was upregulated only by MC58siaD." (PMID 37065199, 2023).
adenocarcinoma (7 papers, 2016 to 2024). A common cancer characterized by the presence of malignant glandular cells. "Our study showed that A549 and H1299 cells contained the highest AKT2 expression levels among four adenocarcinoma cell lines tested." (PMID 32873299, 2020). "Furthermore, AKT2 and AKT3, as part of phosphoinositide 3-kinase (PI3K)/AKT/mTOR signaling pathway, have been associated with several adenocarcinomas." (PMID 36982700, 2023). "The adenocarcinoma I1 and carcinoid I2 components of the mixed neoplasm shared the same mutations in BRAF (p.Gly466Ala), NF1 (p.Pro1359LeufsTer19 and p.Glu1928Ter), STK11 (p.Gly188AlafsTer99), and AKT2 (p.Leu52Ter) genes." (PMID 34926584, 2021). "However, a significant decrease in membranous E-cadherin and increase in nuclear AKT2 staining was noted in human adenocarcinomas." (PMID 26434583, 2016). "There was increased nuclear signal in Pten/Rb-null adenocarcinomas (bottom), consistent with a previous report of localization of AKT1 in the cytoplasm and AKT2 in the nucleus of PC-3 cells." (PMID 37292818, 2023). "This analysis demonstrated that lung tumors induced by IGF-IR overexpression expressed markers consistent with adenocarcinomas whether or not AKT2 was present." (PMID 26654940, 2016).
metabolic disorders (5 papers, 2019 to 2025). "On the other hand, the regulation of Akt inactivation is also important since Akt2 activity has also been associated with cardiac function impairment in metabolic disorders." (PMID 31995605, 2020). "The roles of AKT2 and PI3K in metabolic disorders are significant, as both are key components of the insulin signaling pathway." (PMID 41030587, 2025).
bacterial infection (1 paper, 2023). "In our previous study, after bacterial infection, patients with leukocytopenia exhibited abnormal methylation of AKT2." (PMID 37077346, 2023). "However, our results suggested that the PI3K/AKT pathway was not the cause of this condition and that leukocytopenia and abnormal AKT2 hypermethylation were possibly manifestations of immunosuppression during bacterial infection." (PMID 37077346, 2023).
blood cancer (1 paper, 2024). "No previous study has reported information on miRNA-4716–3p, AKT2 mRNA, and associated SNP (rs2304186) regulation in blood cancer patients in Pakistan." (PMID 38577021, 2024). "Addiction, marital status, residence, and family history weren't significantly linked to the AKT2 rs2304186 GT genotype and blood cancer." (PMID 38577021, 2024). "This study intended to examine the probability of miRNA-4716–3p targeting the AKT2 gene as a diagnostic and prognostic marker for blood cancer." (PMID 38577021, 2024). "Additionally, the association between the AKT2 gene polymorphism and blood cancer susceptibility highlights the role of genetic factors in disease pathogenesis." (PMID 38577021, 2024). "In vivo and in vitro research may be required to confirm our observational association studies and reveal the molecular mechanism of the AKT2 rs2304186 SNP's effects on blood cancer risk." (PMID 38577021, 2024). "Our study underscores the potential utility of AKT2 and microRNA-4716–3p as biomarkers for blood cancer prognosis and diagnosis." (PMID 38577021, 2024). "Notably, AKT2 and microRNA-4716–3p expression levels varied across demographic and clinical factors including age, gender, residence, addiction, familial history, treatment, and smoking status, suggesting their promise as a marker for assessing blood cancer risk." (PMID 38577021, 2024). "The study investigated the role of miRNA-4716–3p, rs2304186, and the AKT2 gene in blood cancer pathogenesis." (PMID 38577021, 2024). "miRNA-4716–3p was shown to be significantly downregulated (p = 0.0294), whereas mRNA expression of the AKT2 gene was found to be significantly upregulated (p = 0.0034) in blood cancer patients compared to healthy individuals." (PMID 38577021, 2024). "The results suggested that the rs2304186 and the deregulated expression of miRNA-4716–3p and AKT2 gene at the mRNA level may significantly increase the incidence of blood cancer, particularly in the Pakistani population." (PMID 38577021, 2024). "With an ideal sensitivity and specificity of 100% and 99%, respectively, the combination of the AKT2 gene and miRNA-4716–3p demonstrated exceptional discriminatory ability in differentiating blood cancer from healthy individuals, with an AUC of 0.893 (p < 0.0001)." (PMID 38577021, 2024). "Our findings propose that microRNA-4716–3p may contribute to the development of blood cancer by targeting and controlling the expression of the AKT2 gene, a process that may be modulated by the rs2304186 polymorphism." (PMID 38577021, 2024). "ANOVA and student t-test analysis were performed and the results showed a significant correlation between the AKT2 gene and rural-based patients (p = 0.0310), and patients with no blood cancer family history (p = 0.0270)." (PMID 38577021, 2024).
brain diseases (1 paper, 2024). "Among the genes annotated to SOX2-bound elements, numerous have been associated with astrogliosis and reactive astrocyte proliferation after TBI or other brain diseases, such as Nr2e1, Mmd2, Wnt7a, and Akt2." (PMID 38672150, 2024).
inflammation (1 paper, 2017). Aberrant reaction of the microcirculation characterized by movement of fluid and leukocytes from the blood into extravascular tissues. "We observed that αMSH significantly decreased Akt phosphorylation level (P<0.05), which is consistent with our previous findings that activation of Akt2 signal blunted RES inhibitory adipose inflammation." (PMID 28514752, 2017).
myopathy (1 paper, 2023). A disease of the muscle in which the muscle fibers do not function properly. "At the mRNA level, the essential insulin-dependent metabolic gene AKT2 and the down-regulated genes, namely FOXO3, were significantly upregulated in muscle parts with critical myopathy and without critical myopathy, compared to controls." (PMID 36904071, 2023). "Insulin-dependent genes critical for the insulin signalling pathway upstream of AKT2, such as IGF1 receptor, IRS1, and PI3Kp110a, were markedly down-regulated in patients with or without acutely understrength myopathy compared to controls." (PMID 36904071, 2023).
AKT2 also shares sentences with these, for which no sentence is quoted: kidney diseases (7 papers); periodontitis (4); schizophrenia (4); cardiovascular diseases (3); fatty liver (3); Ovarian cyst (3); acute myeloid leukemia (2); cognitive deficits (2); colorectal tumor (2); diabetic cardiomyopathy (2); Hypertension (2); Impaired glucose tolerance (2); metastatic cancer (2); myeloma (2); neurodegenerative disease (2); prostatic intraepithelial neoplasias (2); Proteus syndrome (2); small cell lung carcinoma (2); Stroke (2); uterine cancer (2); acanthosis nigricans (1); acquired lipodystrophy (1); acute lymphoblastic leukemia (1); adrenocortical adenoma (1); alcoholic liver diseases (1); Alzheimer disease (1); amyotrophic lateral sclerosis (1); aneurysm (1); angioedema (1); asthma (1).
A further 61 diseases each share a sentence with AKT2 in 1 paper.